CD44 (CD44 molecule (IN blood group))
Diseases named in the same sentence as CD44 in open-access papers (continued):
Sharing a sentence is not in itself a finding about the gene and the disease.
cancer (continued). "The results indicate that SPP1+ TAMs may interact with cancer cells in a paracrine pattern through expressing and secreting SPP1 then binding to cell-surface receptor CD44, consistent with a previous work, showing that CD44 is the receptor of SPP1 to regulate cancer metastasis." (PMID 34676217, 2021). "pRGO modified with CD44 targeting ligand hyaluronic acid (HA) was used in combination with DOX-loaded mesoporous silica (MS) (pRGO@MS-HA) to generate both pH and NIR-triggered DOX release from the multifunctional nanosystems, showing excellent combined effect in multimodal cancer therapy." (PMID 33804239, 2021). "CD44-HA interaction can modulate a variety of intracellular signaling by forming coreceptor complexes with many RTKs (e.g., EGFR) that induce oncogenic pathways involved in cancer cell invasion, migration, and metastasis in the human MCF7 and TamR breast cancer cells." (PMID 34976811, 2021). "For example, in lung stem-like cancer cells that display positivity of CD166, together with CD44 and EpCAM, the cells were found to be more sensitive to NFκB inhibitors for suppressing the expression of CD166, suggesting a strategy to target this small population of cancer cells for treatment." (PMID 34680335, 2021). "In this work, EVs from three different cancer types were captured with anti-CD63 magnetic beads, followed by the addition of three types of SERS nanotags (i.e. Raman reporter-detection antibody-decorated AuNPs targeting the EV membrane proteins glypican-1, EpCAM, and CD44)." (PMID 34855021, 2021). "Because CD44 lacks kinase activity, it can transduce signals via coupling its intracellular domain to adaptor proteins or kinases such as PI3K, NFkB, or CREB and target downstream genes Survivin, Cortactin, and TGF-b2 all of which are related to cancer cell invasion." (PMID 33505471, 2021). "The identification and enrichment of cancer stem cells have been described in various cancer models, and the methods most commonly involve the detection of specific cell-surface markers (e.g., CD133, CD44, CD24) and cytoplasmic proteins (e.g., aldehyde dehydrogenase, ALDH1)." (PMID 34287231, 2021). "For example, TNFSF12-TNFRSF12A and SPP1-CD44 were shown in LC, CRC, and SCC, indicating that myeloid cells might express and secrete TNFSF12 and SPP1, signaling to their receptors TNFRSF12A and CD44 on cancer cells, respectively." (PMID 34676217, 2021). "The protein–protein interaction analysis also resulted in an association between other EMT-related genes, including N-cadherin with YAP1, CD44, and α-SMA, suggesting that these genes may play a dual role in both the activation of CAFs and stemness in carcinoma cells." (PMID 34680267, 2021). "Nonetheless, there is still controversy of the issue if CD44 or ALDH1 itself may be described as one of the unique molecules for identifying cancer stem cells or not." (PMID 32280305, 2020). "The apparently conflicting effects of EMP3 on proliferation of cancer cells in different tissues may simply reflect the different environments, both internal and external, that interact with the EMP3:CD44 membrane bound signalling complex." (PMID 32678083, 2020). "It was reported that CD44 promoted HCC CSC stemness by regulating natural killer (NK) sensitivity or the tyrosine-protein kinase-Met-class I phosphoinositide 3-kinase-protein kinase B (c-Met-PI3K-AKT) signaling cascade, leading to poor prognoses of cancer and chemoresistance." (PMID 33062675, 2020). "There is still a lack of CD44 gene single-nucleotide polymorphisms (SNPs) combined with IL-33/ST2 pathway single-nucleotide polymorphisms in HCC susceptibility analysis literature, although CD44 and IL-33/ST2 have been reported separately in human cancers." (PMID 33062675, 2020). "It was first mentioned that CD44 and CD133 antibodies could fight against cancer progression." (PMID 33321708, 2020).
cancer (continued). "While CD133+/CD44+ CSCs may have been present in the starting ATC population, they were undetectable in the cancer-derived hiPSCs, indicating that we were not simply witnessing a selection, expansion, and enrichment of CSCs present in the parental cancers." (PMID 32795421, 2020). "Therefore, in order to determine the effect of staging on cancer recurrence, the different levels of soluble CD44, CD44v6, CD44v8-10 and EpCAM in patients with and without recurrence were examined according to staging." (PMID 32039729, 2020). "Apart from that, CD44 also plays an important role in MMP-2 and MMP-9 activation through the binding of proteolytically active MMP-2 and MMP-9 isoforms to the membrane and promoting the cleavage of latent TGF-β, which led to invasion and angiogenesis across various cancer models." (PMID 33335857, 2020). "Several other molecules, including CD44, CD133, CD24, and CD166 are potential cancer stem cell markers that may contribute to CRC progression and metastasis; therefore, we assessed if their expression correlated with that of EPHB3 in the CSC samples and controls." (PMID 32294981, 2020). "CD44 plays not only a role in EMT but also is a dedifferentiation marker that has been formerly reported to be highly expressed in anaplastic lesions and is correlated with cancer stem cells in PDAC and Caveolin 1 which was formerly suggested to be considered as an aggressiveness marker in PDAC." (PMID 32228510, 2020). "Following our initial discovery that CD44 isoform switching is essential for EMT8, other studies have also reported that epithelial cells that predominantly express CD44v demand an isoform switch to CD44s in order for cells to undergo EMT and for cancer cells to metastasize." (PMID 31980632, 2020). "Finally, an orally administered small molecule STAT3 inhibitor Napabucasin, which is currently being tested in several clinical trials against various cancer models, have been shown to decrease both STAT3 activation and CD44 expression in biliary tract cancer cells." (PMID 33335857, 2020). "Moreover, cell surface markers such as CD24, CD26, CD44, CD90, CD133, CD166, CD177, aldehyde dehydrogenase 1 (ALDH1), and epithelial cell adhesion molecule (EPCAM) have been identified as biomarkers of CSCs in various types of cancers." (PMID 33014829, 2020). "Co-localization of CD44 and the cytoskeleton adaptor is found to promote in invasive cancer cells and it is speculated that the ERMs sequester CD44 in the non-raft domain to accelerate the cellular migration." (PMID 32271757, 2020). "Mechanistically, the ESRP1-mediated alternative splicing of the CD44 mRNA stimulates the cystine transporter (x-CT), which is involved in cysteine uptake and the accumulation of reductive glutathione (GSH); this decreases ROS and thereby prevents cancer cell metastasis." (PMID 32967226, 2020). "Consistent with its role in the CD44 + / CD24− population, the knockdown of KMT2C significantly elevated the SFE of SKOV3 (P < 0.01), while the over expression of KMT2C significantly inhibited the SFE of TOV21G, indicating that KMT2C was directly related to the cancer stem cells (p < 0.01)." (PMID 32943985, 2020). "Cell sorting based on CD44 and CD24 expression or ALDH (aldehyde dehydrogenase) activity revealed that most Sox2 high expresser cells were not CD44hi/CD24lo- or ALDH-positive cells suggesting that they were not CSCs (cancer stem cells), though CD44 played a role in Sox2 expression." (PMID 33228022, 2020). "The GSH-induced disassembly of HA-ss-TOS-PTX was validated by TEM, drug release behavior as well as a change of particle size in the reducing environment, while the biological evaluation of HA-ss-TOS-PTX in different cancer cells with distinct CD44 expression was not conducted." (PMID 31894722, 2020). "However, the roles of diverse CD44 isoforms on cancer initiation and progression remain lack of further extensive investigation." (PMID 33303029, 2020).
cancer (continued). "Here, we showed that Ezh2 inhibition by DZNEP could reduce Doc-induced gene expression of cancer stem cell markers (Nanog, CD44 and Sox2), supporting the notion that Ezh2 acts on these genes independent of PRC2 complex." (PMID 30621625, 2019). "Moreover, tocilizumab repressed the MCT-1-induced CD44(+)/CD24(−) subpopulations (55.7%) to the control degree (32.5%), confirming that IL-6R immunotherapy inhibited MCT-1-promoted cancer stemness." (PMID 30885232, 2019). "Therefore, RUNX2 and CD44-ICD are potential targets for anti-cancer therapy, and attenuation of their interaction may validate the regulatory effects of these proteins on cancer migration and progression." (PMID 31331331, 2019). "An immunophenotypic analysis revealed that ZJU-0430 cells were positive for CD24, CD44, CD29 and CD133 expression, and partially positive for CD184, and CD326 expression, and negative for CD34, CD90, CD117, and CD338 expression, similar to the primary cancer cells." (PMID 31367188, 2019). "A two-step procedure, combining sorting out all leukocytes (CD45+) and searching for cells positive for common epitopes of cytokeratins (CK8, CK18 and CK19) and CD44, demonstrated that it was not the presence of cancer cells, but their phenotype that determined patients’ prognosis." (PMID 30056567, 2019). "CD117+CD44+ CSCs were isolated from human EOC HO8910 cell line using a magnetic-activated cell sorting system; murine ID8 EOC suspension sphere cells, which are collectively known as cancer stem-like cells, were acquired from serum-free suspension sphere-forming culture." (PMID 31008116, 2019). "Cancer stem cells of BC strongly express CD44, together with no or very low levels of CD24." (PMID 30691317, 2019). "Although CD44+/CD90+ cells demonstrate radiation resistance and self-renewal capacity that correlate with elevated mEAK-7 protein levels, loss of mEAK-7 alone does not result in enhanced cell apoptosis in human cancer cells." (PMID 31288154, 2019). "Thus, HA can selectively target cancerous cells over-expressing CD44 and many studies have addressed HA-modified nanomaterials as cancer targeting moieties to enhance cancer therapy without side-effects." (PMID 31266194, 2019). "However, as CD44 is expressed in many different cancer cell types, it is not enough specific to be a putative target for GC therapy." (PMID 30380687, 2018). "In addition, they contained numerous cancer stem cells expressing LGR5 and CD44." (PMID 29642386, 2018). "Therefore, bL-mediated downregulation of CD44, ALDH1A1, and DLGAP5 could be an essential mechanism of inhibiting cancer cell proliferation, even though the suppression mechanism by bL is different." (PMID 30513573, 2018). "However, our results above raised the possibility that Zeb1 in the context of a CD44/Zeb1 loop might be critical for CGC formation and in turn cancer cell generation." (PMID 29930325, 2018). "In T2 cells, HPI-1 could significantly decrease in the percentage of CD44+CD24low cells whereas GANT-58 did not alter the percentage of cancer stem cells." (PMID 29734730, 2018). "And CD44 expression could be detected in AR knockdown cancer cells, but not in control group, indicated by western blot results." (PMID 29423076, 2018). "HA might be involved in the conversion of cancer cells into cancer-initiating cells or cancer stem cells, characterized by high expression of ABC transporters and other cancer stem cell markers such as CD44." (PMID 30564299, 2018). "Whether CPM can achieve the same in other cancers should be investigated, since CD44 is not a marker of all cancer stem cells." (PMID 28956452, 2017). "We also confirmed that these anti-cancer agents did not suppress the FOXO3/CD44 axis." (PMID 28507327, 2017). "Consistently, drug-loaded NPs were markedly more cytotoxic to cancer cells overexpressing CD44 than to cells lacking CD44, due to selective internalization, which could be competitively inhibited by excess free HA." (PMID 28212584, 2017).
cancer (continued). "OPN binding to CD44 or integrins has been known to up-regulate the expression or activation of various downstream molecules such as MMP-2, MMP-9, cyclooxygenase-2, and vascular endothelial growth factor, which are essential for determining the oncogenic potential of various cancers." (PMID 29254164, 2017). "In this context, monocarboxylate transporters (MCTs), responsible for lactate transport, their chaperones CD147 and CD44, as well as the glucose transporter 1 (GLUT1) and the pH regulator carbonic anhydrase 9 (CAIX) arise as key players in the metabolic reprogramming of cancer cells." (PMID 28969033, 2017). "Thus, selective targeting of CD44v8-10-positive cancer cells by PDT has a greater translational advantage than targeting a constant region of CD44, such as RG735618, which is also expressed ubiquitously on stromal and fibroblast cells, although it is higher in cancer cells." (PMID 28694503, 2017). "However, with the exception of some anti-CD44 antibodies, which were found to be highly toxic, none of the agents have so far been tested in cancer patients." (PMID 28460475, 2017). "In addition, CD44 has been recognized as a cancer stem cell marker of PDAC and is involved in both multidrug resistance and epithelial mesenchymal transition, which protects cancer cells from chemotherapeutic agents." (PMID 28282922, 2017). "The discovery of CD44+/CD24- cells has generated excitement and led to efforts in multiple laboratories to find vulnerability for this subpopulation, as this subpopulation of cancer cells may represent a therapeutic target to anticancer drugs." (PMID 29190901, 2017). "However, it has been reported that cancer stem cells with increased CD44 expression tend to form the negative feedback machinery in terms of oxidative stress-induced Wnt/beta-catenin signal transduction." (PMID 28912668, 2017). "However, whether CD44+CD24−/low, CD44+CD24−/lowESA+, CD133+, and ALDH1+ cancer cells represent distinct CSC populations, and whether they represent the origin of these cells, remain unknown." (PMID 27335684, 2016). "Since CD44 and CD133 are involved in cancer progression, and CD44 regulates cancer invasion through MT1-MMP, these results suggested that decreased expression of these CSC markers, especially CD44 and CD133, by knockdown of mDia1 may be involved in decreased cell invasion in the 3D environment." (PMID 26893363, 2016). "CD44 is a cell membrane-bound surface receptor that mediates cell-cell and cell-extracellular matrix (ECM) communication, and has been found to be increased in numerous cancer types including breast, lung, colorectal tumors compared to basal expression in equivalent healthy tissue." (PMID 27120809, 2016). "We found that CD133, CD54, CD44 and CD26 is stably expressed in circulating cancer cells of the peripheral blood using FACS analysis and that the CD133+cellular subpopulation could be used as the baseline to select CTCs in patients with CRC due to its high expression." (PMID 27764803, 2016). "To investigate whether cancer stem cell markers were over-expressed in HCC specimens, we retrospectively evaluated the expression levels of five cancer stem cell markers (CD90, CD44, CD133, CD13 and CD24) using IHC in 61 matched human HCC specimens and adjacent liver specimens." (PMID 26735577, 2016). "In addition to EpCAM, a number of other biomarkers, such as CD133, CD44, CD24 and CD13, have been reported as biomarkers of HCC cancer stem cells, and it would be highly interesting to characterize cultured 3D spheroids for these stem cell markers in future studies." (PMID 26880118, 2016). "As CD44 supports both chronic inflammation and cancer progression in many (but not all) experimental models and human diseases, CD44 targeting, e.g., by antibody, was successfully documented in many preclinical studies, such as collagen-induced arthritis (CIA)." (PMID 26904028, 2016).
cancer (continued). "Furthermore, our data demonstrated that the cancer stem cells surface markers phenotype, CD90, CD44 and CD133 decreased when Wnt/β-catenin and Notch were blocked, indicating that Notch or/and Wnt/β-catenin blocking resulted in a differentiation of sphere-forming LCSCs." (PMID 26735577, 2016). "Furthermore, lactate induced cancer cell motility by increasing production of other factors such as transforming growth factor-β2 (TGF-β2), hyaluronan and CD44, which play an important role in integrin activation, angiogenesis, stemness and modulation of stroma." (PMID 26099350, 2016). "Although this difference was not significant, this observation could also support the hypothesis that CD44 is lost in more invasive cancers, although other authors’ observations do not concur." (PMID 25129125, 2015). "We also concluded that the CD44/CD24 combination does not enrich for cancer stem cells." (PMID 26449187, 2015). "Here, we target CD44+ cancer caner stem/progenitor cells with salinomycin resulting in suppress of EMT and metastasis, which has recently been documented to effectively eliminate caner stem/progenitor cells in different types of human cancers in vitro and in xenograft mice bearing human cancers." (PMID 25483103, 2015). "Cancer cells contain constitutive endogenous MIF-HSP90 complexes, and inhibition of HSP90 function results in apoptosis, which can be overridden by ectopic MIF expression In fact, the metastasis-promoting CD44 in PDACs is actually the signaling component of the MIF-CD74 receptor complex." (PMID 26267609, 2015). "However, our understanding of CD44 interaction with different sizes of HA fragments in cancer stem cells (CSCs) from HNSCC is lacking." (PMID 26448762, 2015). "In addition to the work performed with ALDH/CD44, we have also performed extensive testing of three additional putative stem cell marker combinations (CD10/CD24, CD44/CD24, CD10/CD44) to determine if these markers could enrich for cancer stem cells in vivo." (PMID 26449187, 2015). "Hence, it is yet not known if one or several CD44 isoforms can be utilized as markers for radioresistance or even cancer stem cell markers." (PMID 24122205, 2014). "Whether or not CD24+/CD44+ cells represent a potential phenotype of cancer stem cells in HNSCC remains to be determined." (PMID 24612587, 2014). "Therefore, we suggest that CD44 is regulated by the interaction of NF-κB with the cis-element CD44CR1, however, we do not rule out other proteins or regulator regions responsible for the up-regulation of CD44 in cancer and TICs." (PMID 25184276, 2014). "The CM values of the Sca-1+-CD44+ cells, which were likely MSCs, were significantly higher than those of the Sca-1+-CD44- and Sca-1--CD44+ subgroups, which contained the non-cancerous progenitor cells and the non-progenitor cancer cells, respectively." (PMID 24581230, 2014). "Thus, the high percentage of the CD44+ subgroup in the Non-Rec and Rec populations indicated that cancer cells constituted the major part of the tumors." (PMID 24581230, 2014). "Although CD44 is believed to be associated with increased metastatic potential in several other cancer entities, we also could not find evidence for a prognostic value of CD44 tissue expression in SCLC." (PMID 24699516, 2014). "CD44 comprises a family of cell adhesion and signalling molecules that exert pleiotropic effects on important biological processes including proliferation, survival, migration, epithelial to mesenchymal transition (EMT), and cancer metastasis (reviewed by Zöller)." (PMID 24009708, 2013).